WT1 (WT1 transcription factor)
Diseases named in the same sentence as WT1 in open-access papers (continued):
Sharing a sentence is not in itself a finding about the gene and the disease.
nephrotic syndrome (36 papers, 2009 to 2026). A collection of symptoms that include severe edema, proteinuria, and hypoalbuminemia; it is indicative of renal dysfunction. "Reported pathogenic variants in the WT1 exon 9 hotspot that have previously been identified to affect splicing in individuals with nephrotic syndrome and DSDs have shown a predominance for 46,XY individuals." (PMID 40235736, 2025). "DDS and WT1 mutations are typically associated with early-onset nephrotic syndrome, rapidly progressing ESRD, WT, and genitourinary abnormalities." (PMID 40890712, 2025). "Herein, we report a case of nephrotic syndrome and differences of sex development in a patient with novel mutations in WT1 gene." (PMID 40980126, 2025). "Combining kidney organoids and scRNA‐seq, we further dynamically characterized the molecular phenotype of nephrotic syndrome induced by WT1 mutation." (PMID 38810140, 2024). "WT1 is centrally involved in nephrin transcription, and mutations in the WT1 gene are also coupled to nephrotic syndrome." (PMID 36834691, 2023). "Herein, we report a 15-year-old female (karyotype 46, XY) patient characterized by delayed puberty and steroid-resistant nephrotic syndrome, in whom whole genome sequencing showed a mutation in intron 9 of the WT1 gene, c.1447 + 4 C>T." (PMID 36980135, 2023). "The screening for genetic variants in genes associated with nephrotic syndrome, including WT1, should be an integral part of investigations of nephrotic syndromes." (PMID 35211794, 2022). "There is a second report of recurrence in a patient with a de novo heterozygous c.1399C>T:p.Arg467Trp (aka p.Arg394Trp) pathogenic variant in exon 9 of the WT1 gene and early-onset nephrotic syndrome associated with Denys–Drash syndrome." (PMID 34031708, 2021). "We recommend performing bilateral nephrectomies before kidney transplantation in patients with persisting nephrotic syndrome and/or a WT1 dominant pathogenic variant." (PMID 33514942, 2021). "Mutations in the NPHS1, NPHS2, LAMB2, and the WT1 genes are responsible for causing nephrotic syndrome (NS) in two third of the early onset cases." (PMID 30013592, 2018). "The average age of onset of nephrotic syndrome in our cohort is very similar to that reported in other studies suggesting that age cannot explain the low prevalence WT1 mutation in our cohort." (PMID 28068926, 2017). "Mutations in WT1 (Wilm’s tumour 1) are detected in 5–9% of children with SRNS with a higher frequency in those with congenital or infantile onset of nephrotic syndrome and in children with Diffuse Mesangial Sclerosis." (PMID 28068926, 2017). "WT1 was originally identified as a gene mutated in patients with Wilm's nephroblastomas and mutations in WT1 have been shown to be the cause of nephrotic syndrome." (PMID 19652713, 2009). "Pathogenic variants in WT1 are associated with severe nephrotic syndrome that may present as early as the neonatal period." (PMID 40235736, 2025). "Nephrotic syndrome due to pathogenic variants in WT1 is almost always resistant to steroids, manifests in childhood, and may coincide with a spectrum of differences of sex development (DSD)." (PMID 40235736, 2025). "We do not recommend performing routine early nephrectomies but suggest that they are considered in patients with severe complications, despite optimization of conservative treatment, and before transplantation in patients with persisting nephrotic syndrome and/or WT1-dominant pathogenic variants." (PMID 33514942, 2021). "We do not recommend performing routine early nephrectomies but suggest that they are considered in patients with severe complications despite optimal conservative treatment, and before transplantation in patients with persisting nephrotic syndrome and/or a WT1-dominant pathogenic variant." (PMID 33514942, 2021).
nephrotic syndrome (continued). "In human patients as well, steroid-resistant nephrotic syndrome cases have clearly been linked to complex heterozygous mutations of nephrin in both children and adults (19, 28, –, 31), with a combined heterozygous mutation in WT1 being the best described." (PMID 27707879, 2016). "WT1 mutations associated with nephrotic syndrome are restricted to exons 8 and 9, that represent a sort of hot-spot that may be easily investigated." (PMID 21904677, 2011). "Finally, to confirm the importance of WT1‐mediated transcriptional function during podocyte development, we generated cultured and implanted patient‐derived kidney organoids using a nephrotic syndrome patient‐iPSCs that carried a heterozygous missense mutation in WT1 (c.1306A > G, exon 8)." (PMID 38810140, 2024). "Congenital nephrotic syndrome may also be due to WT1 mutations and diffuse mesangial sclerosis." (PMID 21904677, 2011). "In that study, 61 patients with WT1-related steroid-resistant nephrotic syndrome in the PodoNet cohort were evaluated." (PMID 39002031, 2025). "In human subjects, urinary exosomal WT-1 concentrations were significantly higher in FSGS patients compared with healthy volunteers or steroid-sensitive nephrotic syndrome patients." (PMID 36766548, 2023). "In conclusion,WT1 gene testing should be performed to guide treatment for patients with steroid-resistant nephrotic syndrome, especially for isolated cases and female patients." (PMID 35710404, 2022). "A literature search was conducted in China National Knowledge Internet (CNKI), Wanfang Database, and PubMed with “WT1 gene”, “Chinese”, “children”, “isolated”, “steroid-resistant”, and “nephrotic syndrome” as keywords." (PMID 35710404, 2022). "WT1 gene testing should be performed to guide treatment for patients with steroid-resistant nephrotic syndrome, especially for isolated cases and female patients." (PMID 35710404, 2022). "The localization of LC3, a marker of autophagy, was investigated by co-staining with antibodies to WT1, which are expressed in the cytoplasm of glomerular podocytes in nephrotic syndrome." (PMID 31978139, 2020). "Germline heterozygous WT1 mutations have been extensively reported in the literature as the cause of Denys-Drash (DDS) and Frasier (FS) syndromes that are characterized by nephrotic syndrome, genitalia anomalies, and pseudohermaphroditism." (PMID 21904677, 2011). "This etiology usually leads to later onset nephrotic syndrome when compared to other forms of WT1-related SRNS and may include variable gonadal dysgenesis." (PMID 40235736, 2025). "The commonest genes associated with nephrotic syndrome differ at birth (NPHS1, NPHS2, WT1, LAMB2, PAX2, PLCE1), in childhood or adolescence (NPHS1, NPHS2, WT1, LAMB2, SMARCAL1, NUP107, TRPC6, PLCE1) and in adults (COL4A3-COL4A5, GLA, ACTN4, CD2AP, INF2, TRPC6)." (PMID 37578539, 2024). "In addition, WT1 protein expression in urinary exosomes has failed as a biomarker for childhood nephrotic syndrome." (PMID 25310591, 2014). "Other genes up-regulated in the early testis show an overlap with mesonephric development and factors involved in nephrotic syndrome (e.g.,NPHS2,WT1)." (PMID 28459107, 2017). "Urinary exosomal WT-1 levels were also significantly lower in patients in remission from either FSGS or steroid-sensitive nephrotic syndrome, or after steroid treatment in six steroid-sensitive nephrotic syndrome patients." (PMID 36766548, 2023). "For example, mutations of podocyte-associated genes account for approximately 30% of pediatric cases of steroid-resistant nephrotic syndrome with one of the four genes (NPHS1, NPHS2, WT1, and LAMB2) identified in 66% of nephrotic syndrome manifesting within the first year of life." (PMID 31049720, 2020). "When compared with monogenic mutations sharing a common nephrotic syndrome phenotype, the RCAD146 classifier also identified subjects carrying mutations in NPHS1, NPHS2, WT1 (NPHS4), and ADCK4 (NPHS9) as non-RCAD." (PMID 30778115, 2019).
nephrotic syndrome (continued). "However, it should be noted that the parents of the patient are 1st degree cousins, and the parents and other immediate family members are not reported to have any nephrotic syndrome or WT1-related disorders." (PMID 40890712, 2025). "Wilms’ tumor 1 (WT-1), a urinary exosomal biomarker with apparent podocyte specificity, is another promising noninvasive biomarker that can detect early progression and treatment-induced regression of podocyte injury in FSGS or steroid-sensitive nephrotic syndrome." (PMID 36766548, 2023). "In addition, the detection of WT-1, a marker of podocytal injury, may aid in diagnosing FGSG when also steroid-sensitive nephrotic syndrome is considered." (PMID 32849923, 2020). "Indeed, reports indicate a decrease in the expression of WT1 and nephrin in patients with minimal change disease (MCD) and focal segmental glomerulosclerosis (FSGS), suggesting a correlation between the expression of WT1 and nephrin in podocyte function in nephrotic syndrome." (PMID 38542564, 2024).
prostate carcinoma (36 papers, 2006 to 2026). A carcinoma that arises from epithelial cells of the prostate gland. "FGFR1, TACC1 and WT1 gene expression levels were associated with the androgen-independent stage in xenografts and human prostate carcinoma samples." (PMID 17137506, 2006). "Other reports demonstrating a role for WT1 in EMT during epicardial development suggest that its reactivation in prostate cancer epithelial cells may also be associated with EMT in cancer." (PMID 23298185, 2013). "BASP1 is a Wilms' tumor suppressor protein (WT1)-associated factor that can regulate WT1 transcriptional activity and it may be a potential target for prostate cancer therapy." (PMID 23717685, 2013). "The WT1 gene encodes a zinc finger transcription factor, plays an important role for the normal development of urogenital organs, and is overexpressed in various tumors, such as leukemia, colon cancer, breast cancer, prostate cancer, urothelial cancer, and pediatric kidney tumors (Wilms’ tumor)." (PMID 34589578, 2021). "WT1 has been detected in hematologic malignancies and solid tumors (breast, lung, pancreatic and prostate cancers)." (PMID 37812190, 2023). "An inverse relationship between androgen receptor and WT1 expression has been found in prostate cancer cell lines, together with WT1 repression of the androgen receptor promoter." (PMID 37733393, 2022). "The finding that the predicted upstream regulatory genes included HIF1A, WT1, and EZH2 genes, reported to be associated with prostate cancer metastasis, suggests that the approach used had merit." (PMID 24448395, 2014). "Certainly elevated WT1 expression in prostate cancer compared to normal prostate and BPH is consistent with its role as a regulator of key steps in EMT and migration." (PMID 23298185, 2013). "Overexpression of WT1 in human prostate cancer cells inhibited proliferation, but the expression of WT1 in leukemic cells enhanced proliferation." (PMID 22133358, 2011). "Functionally, WT1 has been shown to regulate genes important in prostate cancer including VEGF, Bcl2, AR, and IGF1R." (PMID 20426842, 2010). "The relevance of WT1 expression in prostate cancer was confirmed by analysis of tumor tissue and cell lines, suggesting a potential role for WT1 in prostate tumorigenesis." (PMID 20426842, 2010). "One of the transcription factors (TFs) identified in the prostate cancer epithelial cells was the Wilms tumor gene (WT1)." (PMID 18631392, 2008). "Two of the TFs identified in the prostate cancer epithelial cells were the Wilms tumor gene (WT1) and the early growth response gene (EGR1), zinc finger transcription factors that bind at G-rich promoters of genes that regulate growth." (PMID 18631392, 2008). "Overall, this targeted approach identified important candidate binding elements in genes coordinately expressed with WT1 in prostate cancer epithelial cells." (PMID 18631392, 2008). "Analyses of the promoter regions of 11 genes expressed in prostate cancer epithelial cells showed that WT1 TFBS overlapped SP1 and EGR1 TFBS, either separately or together." (PMID 18631392, 2008). "In this study, we identified four candidate genes – FGFR1, MART1, TACC1 and WT1 – by gene expression profiling of different stages of prostate carcinoma in an animal model." (PMID 17137506, 2006). "Using three methods of analysis (DNA microarrays, TMA, and RT-PCR), we have shown that FGFR1, TACC1 and WT1 have much higher levels of expression in human prostate carcinoma than in benign prostate tissue samples, at both mRNA and protein levels." (PMID 17137506, 2006). "We then assessed the expression of four candidate proteins – FGFR1, MART1, TACC1 and WT1 – in human prostate carcinoma samples by IHC." (PMID 17137506, 2006). "Similarly, in NSCLC (non-small cell lung cancer) and prostate cancer, WT1 inhibits Cdh1 and promotes invasion." (PMID 36864480, 2023).
prostate carcinoma (continued). "However, WT1 expression is significantly increased in prostate cancer but is poorly correlated with AOC1 in prostate cancer, which makes it difficult to explain why AOC1 expression is significantly depleted in prostate cancer." (PMID 35922412, 2022). "Although the effect of AOC1 on kidney development via WT1 has been reported, its role in prostate cancer remains unknown, but of great interest." (PMID 35922412, 2022). "In our previous studies, we confirmed that recombinant B. longum displaying a mouse WT1 protein inhibited the tumor growth of mouse syngeneic prostate cancer cells in vivo and that its antitumor activity could be augmented by an anti-PD-1 antibody." (PMID 34589578, 2021). "B. longum 420 delivers a great length of WT1 protein (aa117–419), and we previously demonstrated greater antitumor activity of B. longum 420 compared to Db126 short peptide vaccine with adjuvant in a mouse prostate cancer syngeneic tumor model." (PMID 34589578, 2021). "Notably, they included DMRs close to many genes previously implicated in prostate cancer (e.g., NEAT1, MTOR, RHCG, KCNC2, WT1, HOXC12, KMT2B)." (PMID 30318509, 2018). "Indeed, increased expression of WT1 protein was associated with a reciprocal decrease in the expression of IGF-IR protein and receptor number in prostate cancer cells, and downregulation of WT1 increased IGF-IR expression in glioblastoma." (PMID 25884514, 2015). "Importantly, the biological effect of WT1 mediated changes in E-cadherin levels in these prostate cancer cells lines was altered migration, a key step in metastasis." (PMID 23298185, 2013). "Thus, we conclude that WT1 both regulates E-cadherin levels and contributes to the migratory potential of prostate cancer cells." (PMID 23298185, 2013). "This elevated WT1 expression provides evidence for a potential oncogenic role in prostate cancer." (PMID 20426842, 2010). "Additionally this approach identified differential expression of the transcription factor, WT1, in prostate cancer epithelial cells and lead to subsequent characterization of its expression in cell lines and in paired non-neoplastic and tumor frozen biopsies." (PMID 20426842, 2010). "This cell specific expression suggests a potential role for WT1 in prostate cancer." (PMID 20426842, 2010). "Therefore, an up-regulation of WT1 expression in prostate epithelial cells would be consistent with transcriptional modulation of important prostate cancer growth control genes." (PMID 20426842, 2010). "One important finding was the differential expression of WT1 in prostate cancer epithelia cells." (PMID 20426842, 2010). "Since WT1 activates the AR promoter in prostate cancer cells, this suggests that WT1 may directly or indirectly regulate PSA gene expression." (PMID 18631392, 2008). "WT1 could contribute to GATA2 mediated regulation of target genes in prostate cancer cells, if WT1 also physically interacts with GATA2." (PMID 18631392, 2008). "Thus, we identified many TFBS in potential target genes that were co-expressed with WT1 in prostate cancer epithelial cells." (PMID 18631392, 2008). "Overall, this targeted approach rapidly identified important candidate WT1-binding elements in genes coordinately expressed with WT1 in prostate cancer cells, thus enabling a more focused functional analysis of the most likely target genes in prostate cancer progression." (PMID 18631392, 2008). "To rapidly identify coordinately expressed prostate cancer growth control genes that may be regulated by WT1, we used an in silico approach." (PMID 18631392, 2008). "Expression of FGFR1, MART1, TACC1 and WT1 proteins in human prostate cancer." (PMID 17137506, 2006). "Furthermore, Wt1 (Wilms tumor 1) might act as a novel oncogene facilitating development of the lethal metastatic phenotype in prostate cancer." (PMID 25110652, 2014). "Thus, WT1 appears to be linked to EMT, migration and possibly metastasis of prostate cancer cells." (PMID 23298185, 2013).